C20orf203 (chromosome 20 open reading frame 203)
Synonyms: FLJ33706
Tractability: No criterion of Open Targets' tractability assessment is met for any kind of drug.
Gene: Protein-coding gene on chromosome 20 (32,631,625 to 32,673,941, reverse strand). Ensembl gene ENSG00000198547.
Subcellular location: Cytoplasm
Gene Ontology:
Cellular component: cytoplasm
Genetic constraint (gnomAD): Loss-of-function variants: 15 observed, 11.76 expected, observed/expected ratio (o/e) 1.28, 90% interval 0.85 to 1.84. The upper end of that interval is the gene's LOEUF score, 1.84, which puts it in group 6 of 6, group 1 being the genes least tolerant of losing a copy. Missense variants: 228 observed, 197.88 expected, observed/expected ratio (o/e) 1.15, 90% interval 1.03 to 1.29. Synonymous variants: 88 observed, 77.15 expected, observed/expected ratio (o/e) 1.14, 90% interval 0.96 to 1.36.
Homologues: Orthologues: macaque C10H20orf203 (87% identical).
Diseases named in the same sentence as C20orf203 in open-access papers:
C20orf203 is named in the same sentence as 4 diseases in open-access papers, as found by Europe PMC text mining. Sharing a sentence is not in itself a finding about the gene and the disease. The quoted sentences say what the papers report.
migraine (1 paper, 2022). "Interestingly, some of these loci mapped to genes including ITPK1, ZNF462, RPL30P1, ANKDD1B, THADA, ZNF652, and C20orf203 that have been reported as genome-wide significant in the most recent migraine GWAS." (PMID 36672757, 2022).
C20orf203 also shares sentences with these, for which no sentence is quoted: Alzheimer disease (2 papers); Headache (1); nicotine addiction (1).